RAB42 (RAB42, member RAS oncogene family)
Diseases named in the same sentence as RAB42 in open-access papers (continued):
Sharing a sentence is not in itself a finding about the gene and the disease.
tumor (continued). "Collectively, the methylation of RAB42 may be used as an indicator of tumor immune infiltration and targeting RAB42 may be a strategy to improve the efficiency of checkpoint inhibitor drugs." (PMID 35720121, 2022). "Thus, we validated that RAB42 is differentially 432 expressed between tumor and normal tissues using 433 434 immunohistochemistry staining." (PMID 34912698, 2021). "Based on our findings, we analyzed the tumor-promoting effect of RAB42 using bioinformatics." (PMID 34912698, 2021). "In addition, RAB42 expression was observed to be closely correlated with tumor stages." (PMID 36671428, 2022). "However, the roles and regulatory mechanisms for RAB42 in other tumor types remain elusive." (PMID 36671428, 2022). "RAB42 transcriptional expression was positively correlated with immune chemokines such as CCL22 and CCL2, which can be secreted by tumor cells to recruit the Tregs and TAMs respectively into the TME." (PMID 35720121, 2022). "We found that RAB42 was significantly overexpressed in HCC and correlated with tumor stage, grade, and prognosis in HCC patients." (PMID 35720121, 2022). "In this study, by using multiple available databases, we aimed to explore the effects of RAB42 on HCC prognosis, immune infiltration, tumor proliferation, migration, and invasion." (PMID 35720121, 2022). "Collectively, these results suggested that the expression of RAB42 in HCC may promote the infiltration of CAFs, and CAFs may secret the abundant ECM proteins to form a high density of stroma in tumor tissue to promote HCC progression." (PMID 35720121, 2022). "Furthermore, RAB42 expression was positively related to Immune Score, Stromal Score and ESTIMATE Score in most of the tumor types." (PMID 36671428, 2022).
cancer (6 papers, 2021 to 2024). A tumor composed of atypical neoplastic, often pleomorphic cells that invade other tissues. "Although these results differ slightly, the overall correlation analyses suggested that RAB42 overexpression is associated with TIME across various cancer types." (PMID 39101146, 2024). "The results of gene set enrichment analysis (GSEA) showed that RAB42 was associated with various immune cells and cancer-associated fibroblasts infiltration in HCC." (PMID 35720121, 2022). "Many RAB genes are involved in different cancers but RAB42 (Ras-associated binding 42) is seldom studied in GBM." (PMID 35741652, 2022). "The correlations between RAB42 and the immune cells and cancer-associated fibroblasts infiltration were analyzed by TIMER, TISIDB, and GEPIA database." (PMID 35720121, 2022). "RAB42 overexpression has a high diagnostic accuracy of various cancers (AUC > 0.80)." (PMID 39101146, 2024). "RAB42 is linked to cancer prognosis and progression, according to earlier studies." (PMID 36908705, 2023). "However, RAB42 generally showed low mutational frequencies in pan-cancer." (PMID 36671428, 2022). "Although these studies preliminarily uncovered that genetic and epigenetic factors control RAB42 overexpression and implied its clinical prognostic potential, its detailed functions in pan-cancer are rarely investigated." (PMID 39101146, 2024). "RAB42 overexpression is positively correlated with that of the three gene families in most cancer types." (PMID 39101146, 2024). "In this study, we conducted a pan-cancer analysis of RAB42 expression, and investigated its prognostic, immunotherapeutic and chemoresistance-predictive values." (PMID 39101146, 2024). "Considering the critical role of RAB42 in the development of pan-cancer, the role of RAB42 in drug resistance was explored." (PMID 39101146, 2024). "Taken together, these findings suggest that RAB42 serves as both a potential prognostic marker and a therapeutic target for pan-cancer, especially for LIHC." (PMID 39101146, 2024). "Overexpressed RAB42 serves as a potential prognostic biomarker and therapeutic target in pan-cancer, especially in LIHC." (PMID 39101146, 2024). "By combining the data from TCGA and GTEx databases, the expression level of RAB42 across various types of cancers was visualized." (PMID 39101146, 2024). "Further pan-cancer analyses showed that the expression level of RAB42 significantly differs among distinct pathological stages." (PMID 39101146, 2024). "We found that RAB42 overexpression correlates with poor clinical prognosis and can be used to diagnose most types of cancers." (PMID 39101146, 2024). "We found that high expression level of RAB42 induces chemotherapeutic drug-resistance in pan-cancer." (PMID 39101146, 2024). "Here, our results revealed that RAB42 overexpression occurs in pan-cancer, particularly in advanced pathological stages of most cancer types." (PMID 39101146, 2024). "We next used these algorithms to analyze the correlation between RAB42 overexpression and infiltrated immune cells across various types of cancers." (PMID 39101146, 2024). "Although such correlation is differed in certain cancers, the whole expression correlation of RAB42 with m6A RNA MRGs is evident in pan-caner." (PMID 39101146, 2024). "The second major finding in our study is that RAB42 overexpression significantly affects the immune cell function and infiltration patterns across various cancer types." (PMID 39101146, 2024). "All three algorithms revealed that RAB42 expression had a positive correlation with immune cell infiltration among the majority of cancer types." (PMID 36671428, 2022). "In this study, we performed a comprehensive pan-cancer analysis of the roles and regulatory mechanisms of RAB42 using bioinformatics and experiments." (PMID 36671428, 2022). "In this research, we comprehensively analyzed the roles and regulatory mechanisms of RAB42 by pan-cancer datasets." (PMID 36671428, 2022).
cancer (continued). "To explore the possible mechanism of RAB42 cancer-promoting functions, we further performed GSEA and co-expression analysis." (PMID 34912698, 2021). "RAB42 is significantly overexpressed in most cancers with advanced pathological stages." (PMID 39101146, 2024). "Whether RAB42 is a resistant target of paclitaxel plus carboplatin in pan-cancer (especially in LIHC) warrants further investigation in the future." (PMID 39101146, 2024). "Here, we analyze the role of RAB42 in drug resistance in pan-cancer." (PMID 39101146, 2024). "Firstly, we analyzed the alteration frequency of RAB42 in pan-cancer." (PMID 36671428, 2022). "RAB42 could serve as a prognostic marker and therapeutic target in pan-cancer, especially in LIHC." (PMID 39101146, 2024). "Maybe targeting RAB42 is a new promising strategy for cancer therapy." (PMID 36671428, 2022). "The first major finding of our study is that RAB42 overexpression is markedly correlated with prognostic indicators (OS, PFS, DFS and DSS) in most cancers." (PMID 39101146, 2024). "Further analyses revealed that RAB42 overexpression is positively correlated with writer genes TRMT10C, TRMT61B and reader gene DNMT3B in most cancers." (PMID 39101146, 2024). "Overall, RAB42 overexpression is positively correlated with the TMB and HRD across various cancer types." (PMID 39101146, 2024). "A greater understanding of the direct interactions between APOC1, APOE, RAB42, and TREM2 in cancer is, however, required due to the paucity of studies in this area." (PMID 36908705, 2023). "RAB42 overexpression is significantly correlated with weakly infiltrated macrophages, CD8+ and CD4+ T cells, neutrophils, Tregs and dendritic cells across various cancer types." (PMID 39101146, 2024).
RAB42 also shares sentences with these, for which no sentence is quoted: autoimmune thyroid disease (2 papers); breast carcinoma (2); infection (2); bladder urothelial carcinoma (1); breast invasive carcinoma (1); cholangiocarcinoma (1); esophageal carcinoma (1); graft versus host disease (1); head and neck squamous cell carcinoma (1); lung adenocarcinoma (1); mucinous lung adenocarcinoma (1); Pan (1); stomach adenocarcinoma (1); systemic lupus erythematosus (1); testicular germ cell tumor (1); thymoma (1).